TNF (tumor necrosis factor)
Diseases named in the same sentence as TNF in open-access papers (continued):
Sharing a sentence is not in itself a finding about the gene and the disease.
psoriasis (continued). "Because paradoxical psoriasis does not represent true psoriasis as it never relapses upon cessation of anti-TNF, we next asked whether T cells play a role in paradoxical psoriasis." (PMID 29295985, 2018). "Though the exact pathophysiology of pruritus in psoriasis is not yet known, it can be assumed that TNF-a, IL-17, and IL-23, may be involved." (PMID 30560129, 2018). "RNA-seq data from NHK treated with TNF and rhodomyrtone confirmed the inhibitory effect of rhodomyrtone, particularly on the IL-17A/TNF induction of DEFB4, IL36G, and CXCL1, all known to be highly expressed in psoriasis lesions and investigated as potential biomarkers." (PMID 30321197, 2018). "Paradoxical psoriasis appears independently of the underlying disease or the type of anti-TNF agent used and regresses upon discontinuation of therapy, which suggests that paradoxical psoriasis does represent a side effect of TNF blockade and not de novo psoriasis." (PMID 30555460, 2018). "Consequently, TNF blockade inhibits pDC maturation and prolongs their ability to produce IFN-α, providing an explanation for high levels of type I IFN in anti-TNF-induced paradoxical psoriasis." (PMID 29295985, 2018). "In addition to TNF, recent data also suggest an important role for type I IFN in psoriasis." (PMID 29751683, 2018). "Importantly, no relapses were seen upon discontinuation of anti-TNF treatment, which suggests that paradoxical psoriasis does not represent de novo psoriasis." (PMID 29295985, 2018). "In conclusion, serum levels of TNF-α, IFN-γ, IL-2, IL-6, IL-8, IL-18, IL-22, chemerin, lipocalin-2, resistin, sE-selectin, fibrinogen and C3 were significantly elevated and serum level of adiponectin was significantly decreased in psoriasis patients compared to healthy individuals." (PMID 29416693, 2018). "This hypothesis is further supported by evidence that IL-17A inhibition alone is highly effective in psoriasis and PsA in the absence of TNF-α inhibition." (PMID 30109481, 2018). "UVB irradiation inhibits IL-17A/TNF-α-induced IL-6, IL-8, and CXCL-1 production in HDFs by decreasing the expression of IL-17RA and IL-17RC on fibroblasts through TGF-β1/Smad3 signaling pathway, which reveals a new mechanism of the therapeutic action of UVB on psoriasis." (PMID 28217129, 2017). "Psoriasis and metabolic syndrome may develop interdependently due to a shared immunopathogenesis involving chronic low-level inflammation mediated by pro-inflammatory cytokines such as IFN-gamma, IL-17, IL-23, and TNF-alpha." (PMID 28719618, 2017). "Our results confirm that UVB irradiation inhibits IL-17A/TNF-α-induced IL-6, IL-8, and CXCL-1 production in HDFs by decreasing the expression of IL-17RA and IL-17RC on fibroblasts through TGF-β1/Smad3 pathway, which reveals a new mechanism of the therapeutic action of UVB on psoriasis." (PMID 28217129, 2017). "In subgroup analysis, 10 % of patients in placebo, 14.3 % in metformin and 37.5 % of patients in pioglitazone subgroup had no decline or rather increase in the levels of IL-6 and TNF-α, consistent with the relapse of psoriasis in these patients in next 6 months." (PMID 27531132, 2016). "This inflammation was driven by TNF, cell death, non-canonical NF-κB and the adaptive immune system, and might therefore represent a clinically relevant model of psoriasis." (PMID 26701909, 2015). "This revealed that many cytokines previously associated with the psoriasis gene expression profile (e.g., TNF, IFN-a, IFN-g and IL-1 family) are primarily inducing a gene expression response that is not specific to psoriasis, but is instead associated with a broad spectrum of skin diseases." (PMID 26251673, 2015). "Overexpression of miR146a in psoriasis is controlled by the transcription factor NF-κB, and the NF-κB target genes TRAF6 and IRAK are involved in regulating the TNF-α signaling pathway, suggesting that miR146a may control TNF-α signaling in the skin." (PMID 26604920, 2015).
psoriasis (continued). "Indeed, a comparison of gene expression in psoriasis patients between responders to etanercept, a TNF-α inhibitor, and non-responders revealed that the responsiveness is dependent on inactivation of the Th17 immune response." (PMID 25384035, 2014). "Furthermore, as found in human psoriasis, TNF-α was overexpressed in psoriasis-like skin lesions of K5.Stat3C mice, although virtually no TNF-α was found in untreated control skin." (PMID 25384035, 2014). "Etanercept is an anti-TNF drug that can effectively resolve psoriasis, but not all patients show strong improvement while the condition of some may actually worsen." (PMID 23915137, 2013). "Interestingly, stimulation of keratinocytes with a combination of IL-17A, IL-22 and TNFα increased S100A7 production, which may form a feed-back loop, amplifying inflammation in psoriasis and other conditions." (PMID 23285311, 2012). "Recently, an inflammatory mDC known as Tip-DC (TNFα-inducible nitric oxide synthase-producing dendritic cells) has been found in elevated amounts in psoriasis plaques compared with nonlesional skin from psoriasis patients and normal skin." (PMID 22217359, 2012). "However, in the uninvolved skin of patients with early-onset psoriasis, the ability of LCs to migrate in response to topical exposure to the contact allergen diphenylcyclopropenone, and to the cytokines TNF-α and IL-1β, is absent." (PMID 21933242, 2012). "More recently, a further retrospective study conducted in Taiwan, an intermediate TB burden country, has assessed the accuracy of QFT in 147 psoriasis patients, including both cases with and without treatment with TNF-alpha blocking agents (median exposure of 24 weeks)." (PMID 22645622, 2012). "Moreover, TNF-α stimulates CD11+ inflammatory DCs to produce IL-23 and IL-20 and appears to be a critical cytokine for many of the clinical features of psoriasis, including keratinocyte hyperproliferation, endothelial cell regulation, and recruitment/effector function of memory T-cells." (PMID 22645622, 2012). "Our findings thus suggest that psoriasis mouse models can be differentiated with respect to a TNF-α/IFN-γ/IL-6 axis, which ultimately, may be reflective of disparities in the abundance of certain TNF-generating immunocytes (e.g., macrophages, DCs or T-cells)." (PMID 21483750, 2011). "Other psoriasis-related cytokines contain the miR-369-3p target sequence, and it is intriguing, therefore, to speculate that miR-369-3p plays a role also in regulating other mRNAs containing the same ARE sequence as TNFα." (PMID 20594301, 2010). "Although no clear priority is established between TNF or IL-17 inhibitors, it is recommended that a monoclonal antibody against TNF should be preferred in patients with a history of recurrent uveitis or active IBD, whereas an IL-17 inhibitor may be preferred in patients with significant psoriasis." (PMID 40615873, 2025). "Therefore, reliance on a single IL-17, IL-23 and TNF-α inhibitor may not sufficiently address the diverse critical pathways involved in psoriasis, potentially resulting in suboptimal outcomes in targeted therapy." (PMID 40303401, 2025). "Additionally, DNT cells secrete cytokines such as IL-1, IL-8, IL-10, IL-17, TNF-α, and IFN-γ, which can either facilitate immune homeostasis or exacerbate disease activity in conditions such as autoimmune lymphoproliferative syndrome, Sjögren’s syndrome, systemic lupus erythematosus, and psoriasis." (PMID 40443662, 2025). "Autoantibody production during treatment with tumor necrosis factor (TNF) inhibitors is a recognized phenomenon, however, the production of autoantibodies associated with antiphospholipid syndrome (APS) has not been comprehensively evaluated in patients with psoriasis." (PMID 38987260, 2024).
psoriasis (continued). "Specifically, the proliferation rate was notably increased after stimulating with TNF-α/LPS, while BAC suppressed the proliferation and pro-differentiation in a dose-dependent manner, indicating that BAC could be a promising agent for the treatment of psoriasis." (PMID 37298949, 2023). "However, the dominant immune response in psoriasis is T helper 17 (Th17), whose characteristic cytokines are interleukin 17A (IL-17A), interleukin 17F (IL-17F), interleukin 21 (IL-21), interleukin 22 (IL-22), interleukin 29 (IL-29), interleukin 8 (CXCL-8), and tumor necrosis factor α (TNF-α)." (PMID 38001807, 2023). "Because PDE4 determines several inflammatory pathways in psoriasis, we hypothesized that inhibition of PDE4 by apremilast would result in a greater improvement of endothelial glycocalyx integrity, vascular and LV myocardial function compared with TNF-α inhibitor or cyclosporine treatment." (PMID 35215285, 2022). "Optimistic reports (case reports, case series, and small clinical trials) suggest thiazolidinediones (TZDs) may provide clinical benefits for psoriasis through a decrease of cytokine production including TNFα; however, TZDs have not been consistently shown to improve disease severity." (PMID 34816303, 2022). "Although both MICA and TNFA genes have a high degree of polymorphism, and their allelic diversity has been reported in association with some autoimmune diseases, including psoriasis and with response to anti-TNF treatment, rs2523497 and rs1800610 have never been associated with psoriasis condition." (PMID 36423071, 2022). "Furthermore, we confirmed that IFNγ-sEVs reduced psoriasis symptoms including thickness, erythema, and scales of skin lesions; exhausted Th17 cells, increased Th2 cells; and reduced enrichment of inflammatory cytokines such as IL-17A, IFN-γ, IL-6, and TNF-α in both spleen and skin lesions in vivo." (PMID 35359454, 2022). "However, unlike psoriasis, TNF has not classically been considered a central mediator in AD." (PMID 36605199, 2022). "Additionally, the types of anti-TNF agents did not influence psoriasis development in IBD patients." (PMID 35801760, 2022). "However, the administration of humanized monoclonal antibodies against IFN-γ and TNF-α does not significantly improve psoriasis, suggesting that Th1 cells or their related cytokines may not be critical in the pathogenesis of psoriasis." (PMID 34975883, 2021). "Although the role of the BT-measured microbiome in patients with psoriasis and NAFLD has not been evaluated so far, in our study BT was associated with a higher estimated inflammatory response (elevation of proinflammatory cytokines TNF-α and TGF-β) in patients with versus without NAFLD." (PMID 33883616, 2021). "Upregulation of TNF-α expression is in line with the increased fraction of CD14+HLA-DR−/low MDSC/ CD14+ cells seen in psoriatic BS syndrome patients, suggesting that elevated Mo-MDSCs in patients with psoriasis may be involved in the suppression of T-cell activity." (PMID 32382290, 2020). "According to a cross-sectional study, psoriasis patients had increased proinflammatory macrophage type 1 (IL-1, IL-6, TNF-α), Th1 (IL-2, IL-12, IFN-γ), Th17 (IL-6, IL-17) but also anti-inflammatory Th2/T regulatory (Treg) (IL-4, IL-10) profiles which may be correlated to the severity of psoriasis." (PMID 31649677, 2019). "Therefore, the aim of the present study was to evaluate the pattern of the adaptive immune response in patients with stable severe psoriasis without treatment and patients undergoing systemic therapy with methotrexate or anti-TNF agents at different intervals of the therapeutic cycle." (PMID 31101850, 2019). "A still significantly large group of patients with psoriasis, PsA or RA do not reach the remission status despite the notable improvement of the clinical outcome following the introduction of biologic agents such as TNFα blockers and those targeting the IL-23/IL-17 axis." (PMID 30871134, 2019).
psoriasis (continued). "Additionally, heat shock proteins (HSPs), such as HSP27, HSP60, HSP70, and HSP90, are overexpressed in KCs of psoriasis patients, and these HSPs can function as autoantigens to activate antigen-presenting cells (APC) through TLR4 to promote APC maturation and secretion of TNFα and IL12." (PMID 31815151, 2019). "Thus, the successful outcome of TNF-α’s blocking biologics in treating psoriasis is not surprising." (PMID 31137673, 2019). "However, in the absence of TNF the mice still developed psoriasis, albeit more slowly." (PMID 26701909, 2015). "As many inflammatory and autoimmune diseases, such as RA, Crohn's disease, psoriasis, ankylosing spondylitis and perhaps asthma, require abnormally high levels of TNF-α for pathogenesis, interference in its production by nontoxic natural compounds such as Perna and DMG may likely prove beneficial." (PMID 17562016, 2007). "In this study of patients initiating biologics for treatment of psoriasis, the blood cell biomarker NLR was lower at baseline in responders than in non-responders to treatment with TNF-α inhibitors." (PMID 37047086, 2023). "In a recent case series involving 150 patients with psoriasis who received treatment with TNF-α inhibitors, 10 patients developed paradoxical psoriasis (PP) without stopping anti-TNF-α therapy." (PMID 37175894, 2023). "Furthermore, CD and psoriasis share seven non-HLA susceptibility loci, and the most important susceptibility locus for psoriasis is located on chromosome 6-p21, which is very close to the one implicated in CD pathogenesis (IBD-3 p23) and to the TNF-α encoding gene." (PMID 38003284, 2023). "Moreover, an increased and imbalanced cytokine production—such as interleukin (IL) 17 and tumor necrosis factor (TNF) α—as well as an unopposed type I interferon production, and a change toward a helper T cell 1/helper T cell 2 profile, may all play a role in HS and psoriasis." (PMID 35203664, 2022). "As a secondary objective, we intended to assess the potential differences in genetic background between anti-TNF-induced PPP and the different clinical types of non-induced psoriasis, including psoriatic PPP." (PMID 36143237, 2022). "Differences exist in various TNF-α antagonists, and the therapeutic strategy of TNF antagonists is not required to be changed in the event of psoriasis." (PMID 34678884, 2021). "This is unlike the TNF-α inhibitors that were already approved for Crohn’s disease and/or a range of rheumatic diseases (including PsA) when receiving FDA approval for psoriasis." (PMID 29104241, 2017). "The circulating concentrations of TNF-α, RANKL and OCs in patients with both erosive and nonerosive PsA were higher than those in the psoriasis controls." (PMID 23144698, 2012). "However, correlation analysis revealed that psoriasis presence did not significantly correlate with inflammatory biomarkers such as ROS (r = 0.08, p = 0.21), CRP (r = 0.11, p = 0.12), TNF-α (r = 0.09, p = 0.18), or IL-6 (r = 0.07, p = 0.23)." (PMID 41216079, 2025). "In the same study, TNF-a, IL-17A, and IL-12 (but not IL-23) serum levels were positively correlated with HADS anxiety (HADS-A) scores, while psoriasis patients with anxiety had increased serum TNF-a and IL-17A compared to those without the psychologic comorbidity." (PMID 37240864, 2023). "Therefore, we introduced a novel combination of cytokines, including IL-17A, IL-22, IFN-γ, TNF-α, and KGF as a CytoMix, that had not been previously applied for inducing psoriasis-like inflammation." (PMID 38132145, 2023). "Biologic therapy targeting tumor necrosis factor (TNF)-α, interleukin (IL)-23, and IL-17 may improve not only psoriasis but also cardiometabolic diseases." (PMID 36902720, 2023). "Additionally, we searched for differences in skin CNVs between anti-TNF-induced PPP and different non-induced clinical types of psoriasis, including idiopathic PPP." (PMID 36143237, 2022).
psoriasis (continued). "TNFi (TNF-α inhibitors) are still frequently represented as the first line bDMARDs used in RA, PsA and AS, as well as in many non-rheumatic diseases such as IBD, psoriasis, immune-mediated uveitis and hidradenitis suppurativa." (PMID 36672830, 2022). "HaCaT cells represent an immortalized keratinocyte cell line and are considered as not very suitable for psoriasis research, because IL-17A or IFN-γ and TNF-α stimulation did not increase the expression of inflammatory markers (e.g., STAT3) or enhance cell proliferation in these cells." (PMID 33801280, 2021). "Our study suggests that chronic inflammation, represented by higher levels of TNF-α and TGF-β, and non-viable BT could contribute to the development of NAFLD in patients with psoriasis." (PMID 33883616, 2021). "In addition, it is not currently known whether ARE-directed regulation of TNFα is triggered by miRNAs in skin, as was shown for miR-16 and miR-369-3p in human cell cultures, and whether such interactions may apply to other cytokines and could be involved in the pathogenesis of psoriasis." (PMID 20594301, 2010). "The percentages of patients with PsA attaining a Physician's Global Assessment of psoriasis of "Clear/Almost clear" increased from 33.3% to 61.0% for patients with prior IFX and/or ETN treatment and from 34.6% to 69.7% for patients without anti-TNF therapy." (PMID 20553600, 2010). "It has been observed that the transcription of C6orf10 in keratinocytes can be triggered by TNF-α (Gene Expression Omnibus dataset number: GDS1289), an important proinflammatory cytokine in the pathogenesis of psoriasis, although the function of the C6orf10 product is not known." (PMID 19680446, 2009). "The significant induction of TNF-α increased IL-6, IL-8, EGF, HGF, TGF-α, epiregulin, and amphiregulin, but the increase in these cytokines and growth factors were not different among normal skin, uninvolved, and involved psoriasis." (PMID 20161853, 2009). "Also, in mice treated with the nanoemulsion gel, there was a significantly higher reduction of the Psoriasis Area and Severity Index (PASI) score without signs of skin irritation in any group, whereas the levels of IL‐6 and TNFα showed a maximum reduction in this treatment group." (PMID 40616290, 2025). "However, a large cohort study conducted on 8471 patients with RA, ankylosing spondylitis, psoriatic arthritis, psoriasis, and IBD showed that anti-TNF-α therapy does not increase the occurrence of ILDs among patients with autoimmune diseases when compared to non-biologic treatments." (PMID 37175894, 2023). "Therefore, the difference found in RASGRF1 CNV between anti-TNF-induced PPP and non-induced psoriasis could be related to the fact that two of the patients developing induced psoriasiform reactions presented RA." (PMID 36143237, 2022). "In psoriasis, the absence of Th2-defining cytokines [interleukin (IL)-4, IL-5, and IL-10] and the increased presence of Th1 cytokines (interferon gamma (IFN-γ), tumor necrosis factor (TNF) and IL-12) prompted researchers to classify psoriasis as a Th1-mediated disease." (PMID 31019502, 2019).